INS (insulin)
Diseases named in the same sentence as INS in open-access papers (continued):
Sharing a sentence is not in itself a finding about the gene and the disease.
Hyperglycemia (continued). "Glucose metabolism disorders are characterized by chronic hyperglycaemia and are mainly caused by defects in insulin secretion, insulin action, or both." (PMID 35956345, 2022). "Insulin often at high doses is frequently required to manage hyperglycaemia associated with SARS-CoV-2 infection during hospitalisation." (PMID 35256883, 2022). "It is divided into two types, type 1 DM, in which there is hyperglycemia due to an absolute insulin deficiency, and type 2 DM, which is also characterized by hyperglycemia due to relative deficits in insulin secretion and action." (PMID 36362578, 2022). "While low insulin-stimulated transport of glucose into skeletal muscle is a key etiological factor in T2D, the resulting hyperglycemia is also a fundamental cause of pathophysiology." (PMID 35883827, 2022). "Deficiency in insulin secretion also adversely affects certain metabolic pathways, leading to hyperglycemia." (PMID 36355096, 2022). "Failure in insulin production, insulin tissue-sensitivity, and/or insulin signaling is a pathophysiological hallmark of pre-diabetic states, resulting in hyperglycemia due to impaired uptake of glucose by cells and deregulation of hepatic glucose production." (PMID 35406040, 2022). "Pathological features of type II DM are characterized by hyperglycemia arising from various causes such as a relative deficiency of insulin secretion, insulin resistance, or other malfunctioning factors on carbohydrate metabolism." (PMID 35836679, 2022). "There is accumulating evidence that β-cell decline is primarily driven by increasing hyperglycaemia, which results in both a dramatic loss of insulin content and a decrease in β-cell metabolism." (PMID 36376280, 2022). "The pathophysiology of macrosomia can be explained by the maternal hyperglycemia caused by insulin resistance, leading to elevated placental glucose transport and endogenous fetal insulin secretion." (PMID 36034428, 2022). "Loss of insulin positivity was consistent with hyperglycemia of recipients following adoptive transfer with diabetogenic NOD splenocytes." (PMID 35015736, 2022). "Within 24–48 h after the onset of hyperglycemia, the health of diabetic mice deteriorated, reflected by rapid weight loss, unless provided exogenous insulin." (PMID 35641781, 2022). "Testing 1-h PG at insulin discontinuation identifies individuals at high risk of developing hyperglycemia relapse." (PMID 35721763, 2022). "A number of studies have investigated the association between WFS1 gene polymorphism and insulin secretion, insulinemia, insulin sensitivity, as well as risk of hyperglycemia and T2DM." (PMID 35207731, 2022). "Implantation of the generated cells normalizes hyperglycemia associated with insulin secretion from grafts in rodent type 1 diabetes models." (PMID 35304548, 2022). "Critically, autoreactive T cells firsthand attack β-cell in islet, that results in the deficiency of insulin in bloodstream and ultimately leads to hyperglycemia." (PMID 36405706, 2022). "They exhibit severe hyperglycemia associated with a marked decrease in insulin-secreting capacity due to tissue damage of the pancreatic islets as a major pathology of T2DM." (PMID 36008962, 2022). "Hyperglycemia usually results from a progressive loss of insulin secretion by β-cells in the context of IR." (PMID 35656076, 2022). "The decrease in IR was associated with hyperglycemia due to undelivered signals to the cell, whereas insulin bound to its receptor." (PMID 35369585, 2022). "Hyperglycemia is frequent in patients receiving PN and inadequate blood glucose management as well as insulin administration increase the risk for adverse outcome." (PMID 36992742, 2022). "The diabetogenic allele of the Nidd13/NZO on chromosome 13 induces hyperglycemia in the NZOxB6 backcross population combined with a decrease in the insulin content at later time points." (PMID 35328627, 2022).
Hyperglycemia (continued). "The observed alterations in glucose and insulin hormone in STZ-treated rats are related to the destruction of pancreatic β-cells accompanied by hyperglycemia, hyperlipidemia, and weight loss." (PMID 35529919, 2022). "In conclusion, lower Sg is associated with postprandial hyperglycemia in obese/overweight men, independently of insulin secretion." (PMID 36355105, 2022). "Altered glucose tolerance and hyperglycemia are the main features and are the result of an absolute or relative insulin deficiency or tissue resistance to insulin action." (PMID 35055149, 2022). "The sensitivity of the liver and muscles to insulin is reduced, causing glucose metabolism disorders in these areas and eventually hyperglycemia." (PMID 38647883, 2022). "Hyperglycemia is most common, and its pathogenic principle is caused by abnormal insulin secretion or impaired biological effects." (PMID 35308141, 2022). "DM is a group of metabolic diseases featured with hyperglycemia due to insulin secretion deficiency/insulin action or the two." (PMID 35359881, 2022). "Disruption of insulin secretion causes metabolic disorders, such as hyperglycemia or hypertriglyceridemia, suggesting the important role of insulin in regulating blood sugar homeostasis." (PMID 35328689, 2022). "When a GCK‐MODY affected pregnant woman carries an unaffected fetus, the mild maternal hyperglycemia will cause increased insulin secretion from the fetus, resulting in an excessive insulin‐stimulated fetal growth." (PMID 36483860, 2022). "T2D is a metabolic disorder that results in chronic hyperglycaemia due to a relative loss of insulin responsiveness." (PMID 35580081, 2022). "IAs are able to first bind the insulin in circulation and therefore disrupt the normal function of insulin and cause hyperglycaemia by serving as a carrier." (PMID 36440205, 2022). "Insufficient levels of vitamin D are associated with hyperglycemia, low insulin sensitivity, chronic inflammation, oxidative stress, and apoptosis." (PMID 35859985, 2022). "This compensatory insulin overexpression was gradually decreased with the apoptosis caused by hyperglycemia in pancreatic islet beta cells." (PMID 35252207, 2022). "As Type 1 diabetes (T1D) is known to be an autoimmune disorder, targeting the immune system in activation and/or suppression has shown promise in reducing beta cell loss and improving insulin levels in response to hyperglycemia." (PMID 35336018, 2022). "Normally, this reduced insulin sensitivity and hyperglycemia are counteracted by a greater insulin secretion causing a state of hyperinsulinemia." (PMID 36360995, 2022). "The related research results of our team also found that the persistent hyperglycemia of largemouth bass after a meal is caused by insufficient insulin secretion (unpublished), which is also the reason for the starch intolerance of largemouth bass." (PMID 36005631, 2022). "The hallmark of T1D is a decreased insulin secretion that is subsequently succeeded by chronic hyperglycemia, which has been implicated in long-term complications affecting several organs, including the kidneys, eyes, heart, nerves, and blood vessels." (PMID 35155683, 2022). "Postprandial or fasting hyperglycemia caused by delayed initial insulin secretion is characteristic of insulin resistance and has been reported to occur in 15% to 20% of obese children." (PMID 35333875, 2022). "Abnormal insulin and glucose concentrations include insulin deficiency, hyperglycemia, and medically induced hypoglycemia." (PMID 36483136, 2022). "This has an insulin-modulating effect on peripheral tissues, such as the liver and skeletal muscle, and causes a rapid drop in mice's hyperglycemia." (PMID 36624877, 2022). "Exposure to NDL-PCB Aroclor mixtures caused hyperglycemia and altered plasma insulin levels in both male and female rodents, although a secondary metabolic stressor was required in females." (PMID 35156417, 2022).
Hyperglycemia (continued). "Hyperglycemia is the main consequence of DM, which results from a deficiency in insulin secretion or degradation of produced insulin." (PMID 35204260, 2022). "Pancreatic β cells secrete insulin in response to a high blood concentration of glucose (hyperglycemia), causing circulating glucose to enter cells." (PMID 35348048, 2022). "Maternal hyperglycemia usually causes fetal hyperglycemia, stimulating the fetal pancreas to synthesize excessive insulin." (PMID 36188641, 2022). "In conclusion, lower glucose effectiveness is associated with postprandial hyperglycemia in the daily life of obese/overweight men, independently of insulin secretion." (PMID 36355105, 2022). "Genetically, diabetic leptin receptor-deficient db/db mice are obese and insulin resistant and display hyperglycemia at an early age and transition from β-cell compensation to failure with a pathophysiological sequence of events similar to human T2D." (PMID 34890851, 2022). "T2DM is a primarily a disease of hyperglycemia due to a deficiency of insulin’s many functions, but serum lipids are also strongly affected by insulin." (PMID 36142760, 2022). "Patients often suffer from both defects in insulin secretion and action, making it unclear which anomaly is the primary cause of hyperglycaemia." (PMID 36671612, 2022). "Long-term hyperglycemia caused by impaired insulin secretion leads to the chronic dysfunction of various tissues, and sustained ischemia and hypoxia leads to myocardial necrosis of varying degrees." (PMID 35928930, 2022). "It is known that inadequate hepatic and diminished pancreatic insulin secretory responsiveness increase the risk of hyperglycemia in stressful episodes, such as sepsis, in preterm infants." (PMID 35012001, 2022). "In another study, it was reported that downregulation of miR-26a in the liver samples of patients with T2D caused impaired insulin sensitivity along with hyperglycemia." (PMID 36297381, 2022). "Long-term hyperglycemia in the fetus can stimulate islet cell proliferation, promote insulin secretion, cause hyperinsulinemia, and then promote protein synthesis and inhibit lipolysis, leading to macrosomia." (PMID 35547007, 2022). "Type 2 diabetes, a complex endocrine and metabolic disorder characterized by hyperglycemia arising from a deficient insulin secretion in the context of insulin resistance, has reached epidemic proportions over the past 50 years." (PMID 36302774, 2022). "Type 1 diabetes (T1D) is a metabolic disorder generally recognised as a result of an autoimmune response that affects insulin-producing β cells in the pancreas, which results in extreme insulin deficiencies and associated hyperglycemia." (PMID 35226685, 2022). "HD patients with IR can have reduced serum insulin concentrations after dialysis, resulting in a relative deficiency of blood insulin, as well as post-dialysis hyperglycemia due to increased hepatic gluconeogenesis capacity following HD removal of toxins." (PMID 34807347, 2022). "As a result, it is now recognized as a serious metabolic disorder defined by chronic hyperglycemia caused by insufficient insulin secretion." (PMID 35898909, 2022). "Hyperglycaemia in pregnancy is associated with adverse outcomes and pregnant women who require insulin as treatment are at a higher risk of adverse outcomes." (PMID 36078508, 2022). "Using CGM, patients with CKD were found to experience marked glycemic fluctuations with hypoglycemia due to loss of glucose and insulin during haemodialysis (HD) followed by hyperglycemia in the post-HD period." (PMID 35528010, 2022). "It is known as a set of metabolic illnesses marked by hyperglycemia caused by insulin production or insulin function problems." (PMID 35956419, 2022). "A reduction in postprandial hyperglycemia in diabetics will raise their risk of developing macrovascular issues, which can be minimised by the administration of insulin throughout the meal." (PMID 35586686, 2022).
Hyperglycemia (continued). "In diabetic rats, the marked changes in blood glucose concentration, insulin hormone level, and body and liver weights are related to the destruction of pancreatic β-cells which is accompanied by hyperglycemia, hyperlipidemia, and weight loss." (PMID 35345832, 2022). "It is defined as a group of metabolic diseases characterized by hyperglycemia caused by defective insulin secretion, defective insulin action or both." (PMID 36483136, 2022). "Diabetes mellitus is a metabolic disease characterized by hyperglycemia due to insulin deficiency or resistance to insulin action or both, which can be accompanied by long-term microvascular and macrovascular complications, leading to morbidity and mortality." (PMID 35509840, 2022). "Patients with hyperglycemia who received insulin had an equal risk of adverse events compared with those with normal blood glucose levels." (PMID 36088294, 2022). "Fifty percent of patients with MODY5 have a whole gene deletion of HNF1B which is associated with severe pathology, elevated HbA1c, hyperglycemia, and decreased insulin secretion with progressive pancreatic β cell dysfunction." (PMID 36573710, 2022). "It is a set of metabolic diseases featured with hyperglycemia due to insulin secretion deficiency or insulin action or the two." (PMID 35359881, 2022). "Hyperglycemia is caused by increase of insulin resistance in insulin target tissues and/or decrease of insulin secretion from pancreatic β-cells." (PMID 35918386, 2022). "Increased fasting plasma insulin levels, observed in tau KI mice, can be caused by a compensatory mechanism induced by hyperglycemia that leads to an increase of β-cell mass." (PMID 35250480, 2022). "Maternal intermittent hyperglycemia leads to fetal hyperglycemia and fetal release of insulin, insulin-like growth factor and growth hormone which cause an increase in fetal fat deposition and weight gain." (PMID 35956308, 2022). "Type I diabetes is developed in children due to the autoimmune attack of beta cells that secret insulin leading to its deficiency and hyperglycemia; therefore, it is mainly treated with insulin." (PMID 36544223, 2022). "The ensuing insulin deficiency and hyperglycemia require alternative exogenous insulin injections, which however cannot hold up the progression of autoimmune response and the life expectancy shortening of T1DM patients with complications." (PMID 35964125, 2022). "In contrast, in both pregnant sheep and mice, administration of the natural GC before term increases food intake and alters glucose-insulin dynamics causing maternal hyperglycemia and hyperinsulinemia with implications for placental nutrient transfer." (PMID 35684104, 2022). "In case of severe hyperglycemia (glycated hemoglobin > 9.0%) accompanied by hyperglycemia symptoms, including polyuria and weight loss, hypoglycemic agents or even insulin injection are used to lower blood sugar." (PMID 35357351, 2022). "Among these, hyperglycemia, insulin resistance, and insulin damage caused by inflammatory cytokines and oxidative stress are the primary reasons." (PMID 36297069, 2022). "Hyperglycaemia can cause advanced IR and a responding failure of functional pancreatic beta cells (islet failure) to preserve appropriate insulin output and compensate for decreased insulin sensitivity." (PMID 36532559, 2022). "The liver is the main site of INS resistance and INS resistance can lead to elevation of gluconeogenesis and reduction of glycogen synthesis in the liver, and then cause hyperglycemia." (PMID 36119371, 2022). "In summary, both the in vivo and epidemiological data suggest that OCPs cause hyperglycemia, but more studies are needed to investigate the impact of OCPs on plasma insulin levels." (PMID 35156417, 2022). "The SIDT1 gene is associated with insulin secretion, and its expression was decreased in individuals with hyperglycemia." (PMID 36046788, 2022).
Hyperglycemia (continued). "KATP channels for potassium, which are expressed in pancreatic β-cells with a role in insulin secretion, are altered in case of mutations in this gene, thereby leading to hyperglycemia." (PMID 35565885, 2022). "With the higher percentage of β-cell destruction, there will be little insulin production, thus causing hyperglycemia." (PMID 35369585, 2022). "We have shown that there are three subtypes of GDM according to the heterogeneity in the physiological and pathological processes leading to hyperglycemia, which show different characteristics, risk factors, and insulin sensitivity alteration patterns." (PMID 36530712, 2022). "Hyperglycemia is the main characteristic caused by insufficient insulin secretion and poses a serious risk to human health." (PMID 36268149, 2022). "DM is diagnosed as a result of an elevated blood glucose level (hyperglycaemia) caused by inadequate insulin secretion, defective insulin action, or both." (PMID 36013325, 2022). "We found that corticosteroids (>20 mg/kg hydrocortisone), but not low-dose corticosteroids, increased the risk of myocardial infarction and hyperglycemia requiring insulin infusion in adults." (PMID 35722531, 2022). "HFD increased body weight-induced hyperglycemia and dyslipidemia and caused resistance to insulin while reducing the level of insulin-degrading enzyme (IDE)." (PMID 36304965, 2022). "In our study, patients on insulin had a lower risk of mortality to hyperglycemia than patients on OHA or diet." (PMID 35842591, 2022). "When hyperglycemia and impaired insulin expression causing diabetic retinopathy are considered, the low Adipsin levels are consistent with literature and are an expected finding." (PMID 35436912, 2022). "Type 1 diabetes (T1D) is characterized by autoimmune destruction of the insulin-producing beta cells in the pancreas, resulting in a loss of circulating insulin and subsequent hyperglycemia." (PMID 35448529, 2022). "Chronic hyperglycaemia causes a dramatic decrease in mitochondrial metabolism and insulin content in pancreatic β-cells." (PMID 36376280, 2022). "Hyperglycemia is the typical characteristic of DM, which is mainly caused by defective insulin secretion or/and impaired insulin biology." (PMID 35295328, 2022). "Streptozotocin (STZ) is an alkylating agent toxic to insulin-producing pancreatic beta cells, and its injection into mice or rats provokes insulin deficiency and hyperglycemia." (PMID 35495933, 2022). "Postprandial hyperglycemia causes a cascade of changes, including hyperinsulinemia, glucose uptake by insulin-sensitive tissues, concurrent hypoglycemia to levels lower than fast values, greater appetite driven by the lack of available fuel, and overeating." (PMID 36110403, 2022). "Overall, our results illustrate that unregulated ERRα activity in the ERRα3SA mice leads to postprandial hyperglycemia partly caused by impaired insulin-stimulated glucose disposal as well as increased hepatic inflammation and oxidative stress." (PMID 35440636, 2022). "Defective insulin action and/or secretion results in metabolic abnormalities and the associated chronic hyperglycaemia results in long-term damage leading to organ failure." (PMID 35475576, 2022). "T2DM is characterized by hyperglycemia resulting from insulin deficiency caused by pancreatic β-cell dysfunction and insulin resistance in insulin-sensitive tissues such as liver, muscle, and adipose tissue." (PMID 35893259, 2022). "Insulin defect and less glucose tolerance can lead to chronic hyperglycemia which will disrupt many signaling cascades cause the body tissues to utilize glucose in blood." (PMID 36079819, 2022). "In HEC-1A, both in hypoglycemia and hyperglycemia conditions, insulin stimulation caused at first an increase in BMI-1 protein level and then after prolonged stimulation the level of BMI-1 decreases." (PMID 36497428, 2022).